MLANA (melan-A)
Diseases named in the same sentence as MLANA in open-access papers (continued):
Sharing a sentence is not in itself a finding about the gene and the disease.
metastatic melanoma (26 papers, 2012 to 2026). A melanoma that has spread from its primary site to another anatomic site. "Histopathological analysis of samples obtained via endoscopic ultrasound (EUS)-guided porta hepatis biopsy and ureteral tumor debris collected during cystoscopy confirmed Melan-A and S-100-positive metastatic malignant melanoma." (PMID 41815625, 2026). "Melan-A has a sensitivity of 85%-97% for primary and 57%-92% for metastatic melanoma and a specificity of 95%-100%." (PMID 40860834, 2025). "The possibility of primary or metastatic melanoma should be considered in differential as it is notorious for its atypical presentation and markers such as Melan A, HMB45, MITF, S100 are helpful in clinching the diagnosis." (PMID 38438897, 2024). "We profiled CD56 expression in a paired histological section of metastatic melanoma LN and identified clusters of MLANA-positive cells expressing CD56 that were organized in circular shapes." (PMID 37563418, 2023). "In this context, we previously documented clinical responses in half of metastatic melanoma patients after adoptive transfer of T-cell clones specific for the Melan-A/MART-1 antigen." (PMID 34120214, 2021). "In terms of safety, Melan-A expression being restricted to the melanocytic lineage, the injection of T-cells specific reactive against this antigen may cause vitiligo by killing normal melanocytes which is an acceptable adverse effect considering the severity of metastatic melanoma." (PMID 34120214, 2021). "Immunohistochemical analysis has been shown to be useful in identifying metastatic melanoma; the sensitivity of S100, Melan A, and HMB-45 are reported to be 97–100%, 75–92%, and 69–93%, respectively." (PMID 31134450, 2019). "An excisional biopsy of the left axillary node showed metastatic melanoma with extensive large cell involvement, S100 positive, Melan-A positive, and HMB-45 positive." (PMID 29520339, 2018). "TILs from an HLA-A2+ metastatic melanoma patient were incubated with brefeldin A and monensin ± autologous tumor for 4 h prior to staining with Melan A tetramer and intracellularly with anti–IFN-γ Ab." (PMID 25452566, 2015). "Our patient's sigmoid colon mass was amelanotic but stained positive for melan-A, also commonly found in metastatic melanomas." (PMID 25093125, 2014). "High frequencies of circulating CD8+ T lymphocytes were detected in patients with metastatic melanoma, specific for Melan-A/MART-1, MAGE-10, and Ny-Eso-1, and CTL have also been found infiltrating melanoma metastases." (PMID 23616948, 2013). "Two other groups have shown that Melan-A-specific CD8+ T cells were able to induce long-lasting responses in metastatic melanoma patients and that transferred cells persisted and even expanded in vivo." (PMID 22909342, 2012). "Interestingly, a patient with metastatic melanoma treated with Melan-A-specific CD8+ lymphocytes developed partial depigmentation associated with skin localization of the infused T cell clones." (PMID 31731645, 2019). "Furthermore, the observed pigmentation in lymph nodes of heterozygous mice was Melan A-positive by immunofluorescence, which suggests that metastatic melanoma has occurred." (PMID 31342168, 2019). "Immunohistochemistry was positive for S100, Melan-A, and SOX10, with a high Ki67 proliferation index of 90%, confirming the diagnosis of metastatic malignant melanoma." (PMID 41142597, 2025). "The tumor cells were stained for S100 protein, MELAN A, and HMB45, which led to an initial diagnosis of metastatic malignant melanoma." (PMID 36589177, 2022). "Melan-A and SOX10, a marker used to identify metastatic melanoma, were assessed by qPCR, demonstrating significantly higher values for hPL cultured cells compared to FBS supplemented cells." (PMID 34768746, 2021). "In conclusion, we demonstrated the feasibility and safety of ACT with multimer-sorted Melan-A and MELOE-1 specific T cells to metastatic melanoma patients." (PMID 34120214, 2021).
metastatic melanoma (continued). "Pathology was consistent with metastatic melanoma with tumor cells extensively immunoreactive for HMB-45 and focally immunoreactive for Melan-A and S-100." (PMID 31703593, 2019). "We finally looked for Melan-A and MELOE-1 CDR3α and CDR3ß specific sequences shared between the different populations that originated from distinct metastatic melanoma patients." (PMID 30214446, 2018). "This proliferation was morphologically and immunophenotypically distinct from the patient’s concurrent metastatic melanoma, which consisted of sheets of large, pleomorphic epithelioid cells with expression of HMB-45 and melan-A." (PMID 25928106, 2015). "One of the superficial left inguinal lymph nodes contained metastatic melanoma, confirmed by HMB-45 and melan-A positivity." (PMID 25928106, 2015). "The optimized procedure, validated in 3 blank runs in a clinical setting, allowed the production of at least 108 pure (>90%) Melan-A- and MELOE-1-specific T cells within 28 days starting with 100 mL of blood from metastatic melanoma patients." (PMID 24194775, 2013). "Following emergency tracheotomy, histopathology confirmed metastatic melanoma (HMB-45+, Melan-A+)." (PMID 41852460, 2026). "With the aim to increase the statistical value of antigen-specific repertoire analyses and to smooth individual variations, we analyzed TRAV and TRBV usage of all the Melan-A and MELOE-1 clonotypes (originating respectively from 6 and 4 HLA-2 metastatic melanoma patients)." (PMID 30214446, 2018). "PRAME immunohistochemistry can differentiate nodal nevi from metastatic melanomas, but it is recommended to use prior H&E and other melanocytic markers (SOX 10 or Melan A) to confirm the presence of melanocytes in the sentinel lymph node biopsy or to use double staining PRAME/Melan A." (PMID 39335694, 2024). "Immunohistochemistry was positive for Melan-A, HMB45, vimentin, S-100 protein and negative for cytokeratin, all consistent with metastatic malignant melanoma." (PMID 27906105, 2016). "Lesions were also immunostained for Melan A, HMB45 and Tyrosinase but no positive cells were detected ruling out a possible combination between atypical metastatic melanoma cells accompanied by dense plasma cell-rich lymphoid infiltrates." (PMID 25996609, 2015).
angiomyolipoma (21 papers, 2008 to 2025). A neoplasm with perivascular epithelioid cell differentiation often associated with tuberous sclerosis. "However, cases of ESC-RCC with epithelioid angiomyolipoma characteristics have been reported, and the tumor cells express Melan-A, melanosome-associated antigen, CK20, and PAX8, among which CK20 and PAX8 may be effective for a differential diagnosis." (PMID 37098579, 2023). "Melan-A is also positive in “sugar” cell tumours of the lung, PEComa, and angiomyolipoma; however, these tumours usually present with a characteristic morphology that allows a differential diagnosis on H&E staining." (PMID 40507250, 2025). "In our case, HMB-45 and melan-A were both expressed in both renal and pulmonary tumors, confirming the diagnosis of angiomyolipoma." (PMID 27527652, 2016). "HMB-45 and melan-A are present in angiomyolipoma, differentiating it from other primary and secondary mesenchymal or primary epithelial tumors." (PMID 27527652, 2016). "Histopathologically, the tumor was an angiomyolipoma with positive immunostaining for HMB45 and Melan A. The present case suggests the importance of core-needle biopsy prior to surgical intervention for retroperitoneal fat-containing tumors." (PMID 33029444, 2020). "Surprisingly enough, pathological report of a smaller liver lesion was indicative of angiomyolipoma staining positive for HMB45 and Melan-A." (PMID 30611280, 2019). "Conversely, epithelioid angiomyolipoma will exhibit at least focal labeling for melanocytic markers, including HMB-45, melan-A, and MiTF, as well as usually diffuse labeling for cathepsin K." (PMID 29090117, 2017). "Negative immunostaining for HMB45, Melan A, and S100 in tumor cells also excludes angiomyolipoma and malignant peripheral nerve sheath tumor from the differential diagnosis, respectively." (PMID 38388450, 2024). "Differentiating pure epithelioid PEComa/epithelioid angiomyolipoma from TFEB-rearranged renal cell carcinoma is challenging, as the two entities share the immunohistochemical expression of cathepsin K and melanocytic markers, such as HMB45 and Melan-A." (PMID 34069976, 2021). "In our case, these markers stained positive, whereas nuclear stains for MDM-2 as well as for HMB45 and Melan-A were negative, characteristic markers when positive for angiomyolipoma." (PMID 30611280, 2019). "If such a tumor does not stain for HMB-45 or Melan-A, a specific diagnosis of epithelioid pleomorphic angiomyolipoma cannot be made with certainty." (PMID 23628229, 2013). "Angiomyolipoma reacts with HMB45, Melan-A, tyrosinase and S100 protein." (PMID 24179528, 2013). "ESC RCC can express Melan A, HMB45 or Cathepsin K. PAX-8 positivity rules out an epithelioid angiomyolipoma, in addition to absence of other morphological features of AML." (PMID 34514562, 2022). "Immunohistochemically, epithelioid angiomyolipomas are usually HMB45 positive, melan-A positive, but alpha-inhibin negative." (PMID 35220972, 2022). "We noticed the characteristic co-expression of melanocytic (HMB-45, Melan A), histiocytic (CD68), and smooth muscle (SMA) markers (data not shown), which supports the unique nature of angiomyolipoma as a tumor with the ability for different phenotypic and immunotypic presentations." (PMID 29308833, 2017). "Melan A and HMB45 were negative excluding a melanocytic lesion or an angiomyolipoma." (PMID 18518995, 2008).
vitiligo (18 papers, 2005 to 2026). Generalized well circumscribed patches of leukoderma that are generally distributed over symmetric body locations and is due to autoimmune destruction of melanocytes. "LS lesions showed a significantly higher number of Melan-A-positive melanocytes than vitiligo lesions (SA/EA: 0.007 ± 0.007 vs. 0.003 ± 0.003, p < 0.0001)." (PMID 37521337, 2023). "Both vitiligo associated genes (PMEL, TYRP1, DCT & MLANA) and PD-L1 had mRNA levels near the median value observed across the dataset." (PMID 30832716, 2019). "Here, we labeled Melan-A, a melanocyte marker, toquantify melanocytes in normal appearing non-lesional skin, depigmented lesionalskin and the leading edge skin from vitiligo patients." (PMID 21541348, 2011). "Expression of the MLANA gene can also be detected in the skin of patients with vitiligo." (PMID 31772839, 2019). "It has been reported that vitiligo patients possess highfrequencies of circulating CD8+ T lymphocytes specific for Melan-A, andmelanoma patients who went through Melan-A specific CD8+ T cell infusionimmunotherapy demonstrated melanocyte loss in regions of normal skin." (PMID 21541348, 2011). "Notably, a few recent studies indicated that Melan-A/MART1-specific CD8+ T cells isolated from vitiligo patients possess an increased avidity and exert a superior anti-tumor activity than those from melanoma." (PMID 16135249, 2005). "In addition, Melan-A specific CD8+ T cells with cutaneous lymphocyte antigen have been detected in the peripheral blood of patients with vitiligo, and their number may correlate with disease activity." (PMID 29362715, 2017). "An association between CD8+ T lymphocyte reactivity to the melanocyte antigen gp100, and to a lesser extent Melan A/MART-1, and vitiligo has been demonstrated." (PMID 16303054, 2005). "Melan-A immunostaining demonstrated a complete absence of epidermal melanocytes, confirming concurrent vitiligo rather than LS-related post-inflammatory hypopigmentation." (PMID 41959985, 2026). "Similarly, in vitiligo, CD8+ T cells target antigens from melanosomal proteins such as PMEL, MLANA/MART1, TYR, TYRP1, and DCT." (PMID 37339630, 2023).
cutaneous melanoma (11 papers, 2007 to 2025). A primary melanoma arising from atypical melanocytes in the skin. "Immunohistochemical positivity of oral and cutaneous melanomas by S-100, melan-A, PNL-2, and COX-2 antibodies." (PMID 34513965, 2021). "Studies with formalin-fixed, paraffin-embedded sections of cutaneous melanoma showed positive results for melan-A and tyrosinase in 97% and 90% of the cases, respectively." (PMID 17445277, 2007). "MLANA expression is also useful for diagnosis of invasive cutaneous melanomas." (PMID 26267609, 2015). "Three cutaneous melanoma cell lines (C013M, MeWo and NM177) were classified as transitory, as they expressed elevated levels of MITF and Melan A, and intermediate/high levels of AXL and/or NGFR." (PMID 34073253, 2021). "Notably, many of these genes, such as MLANA, PMEL (HMB45) and S100, correspond to well‐established immunohistochemical markers for cutaneous melanoma." (PMID 41017066, 2025). "Investigating 448 cutaneous melanomas from the TCGA PanCancer Atlas, we discovered a positive correlation between high ATP1A1 mRNA expression and markers of differentiation and pigmentation (MITF, SOX10, TYR, MLANA)." (PMID 38178183, 2024). "Because case 13 grouped near cutaneous melanoma by t-SNE analysis, we evaluated multiple melanocytic markers (HMB-45, Melan-A, MiTF) that were all negative." (PMID 39636306, 2025). "In our patient's, history of cutaneous melanoma, the absence of cystic teratomas lesion and tumor positive stain for PS100 and Melan A markers and negative stain for of alpha-inhibin and CD99 confirmed the diagnosis of metastatic ovarian melanoma." (PMID 21682901, 2011).
clear cell sarcoma (9 papers, 2012 to 2025). A rare malignant neoplasm with melanocytic differentiation characterized by the presence of polygonal or spindle shaped clear cells. "Another important differential diagnosis is clear cell sarcoma of soft tissue; however, CCS lacks melanocytic markers such as HMB-45 and Melan-A, which are commonly found in the soft tissue variant." (PMID 40443852, 2025). "Since Melan-A expression also occurs in the exceedingly rare cases of clear cell sarcoma of the breast, we checked for the frequent translocations EWSR1-ATF1 and EWSR1-CREB1." (PMID 35501497, 2023).
renal cell carcinoma (9 papers, 2017 to 2024). "These tumors demonstrate similar immunohistochemistry results to TFEB translocation renal cell carcinoma, commonly expressing pigment differentiation-related markers (Melan-A, HMB45, and cathepsin k)." (PMID 38730456, 2024). "Melanocytic markers, HMB45 and Melan-A, were respectively positive in 15 of 36 (42%) and 14 of 34 (41%) of MiT family translocation renal cell carcinomas using the 5% cutoff." (PMID 35980471, 2022). "In one-third of all cases, Xp11 translocation renal cell carcinoma focally express melanogenic markers such as Melan-A and HMB45." (PMID 31382581, 2019). "These tumors may show overlapping morphological and immunohistochemical features with MiT family translocation renal cell carcinoma, especially with TFEB-rearranged renal cell carcinoma, both positive for cathepsin K and Melan-A." (PMID 35980471, 2022). "In addition, ectopic adrenal tissue must be differentiated from urogenital tumors, in particular its mimickers, such as renal cell carcinoma and Sertoli Leydig cell tumor, that also partially share the immunophenotypic markers of the adrenal cortex (Melan-A, SF-1, inhibin)." (PMID 34095993, 2021). "The tumor cells were diffusely positive for HMB45, Melan-A, CK20, vimentin antibodies, and TFE3, suggesting that the tumor originated from perivascular epithelioid cells, excluding renal cell carcinoma." (PMID 37675231, 2023). "The expression of Melan-A and HMB45 was significantly lower in TFE3-rearranged renal cell carcinoma compared with TFEB-rearranged renal cell carcinoma, even when a 5% cutoff was used (17% and 27% respectively)." (PMID 35980471, 2022). "Additionally, melanogenesis markers such as Melan-A and HMB45 are found in TFE3-rearranged renal cell carcinoma, although less frequently compared to their occurrence in TFEB-rearranged renal cell carcinoma." (PMID 39410016, 2024). "Moreover, in TFEB-rearranged renal cell carcinoma, cathepsin K and melanogenesis markers are constantly positive, whereas TFE3-rearranged renal cell carcinoma stains for cathepsin K in roughly half of the cases, HMB45 in 8% and Melan-A in 22%." (PMID 35980471, 2022). "TFEB-associated renal cell carcinoma was not marked as an epithelial immunohistochemical marker but was marked as melanocyte markers HMB45 and melan-A." (PMID 36550835, 2022).
adrenocortical carcinoma (8 papers, 2008 to 2024). "Additional immunohistochemical stains showed that the tumor cells were positive for Melan A and inhibin, supporting a diagnosis of adrenocortical carcinoma." (PMID 32375822, 2020). "Immunohistochemically benign and malignant adrenocortical carcinoma are positive for synaptophysin, inhibin, Melan-A, and calretinin." (PMID 25685588, 2015). "Metastases of adrenal cortical carcinoma and hepatocellular carcinoma may be excluded by means of immunohistochemistry (melan-A-cross reactivity in adrenal cortical carcinoma, HepPar in hepatocellular carcinoma)." (PMID 18593459, 2008). "Negative immunostaining for vimentin and Melan-A ruled out an adrenocortical carcinoma." (PMID 37218666, 2024). "In this study, we showed that sarcomatous component of the tumor also focally retains positivity for Melan-A, synaptophysin and calretinin, supporting the notion that sarcomatous area of the tumor has indeed originated from the adrenocortical carcinoma rather than representing a collision tumor." (PMID 20687934, 2010). "Pathology was re-reviewed and immunohistochemical markers for adrenocortical carcinoma (ACC), including inhibin, calretinin, and melan A were negative and adrenals were normal on imaging." (PMID 27171493, 2016).
uveal melanoma (8 papers, 2002 to 2025). A melanoma derived from melanocytes of the uveal tract. "The aim of this study was to investigate the expression of melan-A and tyrosinase in uveal melanoma, and the correlation with radiation therapy or clinicopathological parameters." (PMID 17445277, 2007). "Posteriorly, formalin-fixed, paraffin-embedded sections of uveal melanoma were studied for the expression of melan-A and tyrosinase." (PMID 17445277, 2007). "The aim of this study was to investigate the correlation between radiotherapy or clinicohistopathological parameters and the expression of melan-A and tyrosinase in uveal melanoma." (PMID 17445277, 2007). "Moreover, when tyrosinase and melan-A are used together, 100% of the formalin-fixed, paraffin-embedded uveal melanoma samples tested positive for one of those markers." (PMID 17445277, 2007). "We used Melan A and SOX10 immunohistochemistry tests to identify uveal melanoma cells in the nodules." (PMID 35056909, 2021). "This concise panel replaces less sensitive markers, such as S-100 with SOX-10, and eliminates the redundant use of Melan-A, which has the same sensitivity as HMB-45 for uveal melanoma." (PMID 26316887, 2015). "Interestingly, uveal melanoma, the most common malignant intraocular tumour in adults, can only be partially recognised by the three most widely used immunohistochemical reagents for the diagnosis (HMB-45, S-100 and A103 (Melan-A/Mart-1 specific antibody)." (PMID 12177778, 2002).